HDAC9 (histone deacetylase 9)
Diseases named in the same sentence as HDAC9 in open-access papers (continued):
Sharing a sentence is not in itself a finding about the gene and the disease.
atherosclerosis (continued). "Moreover, compared with Hdac9+/+Apoe−/− mice, Hdac9−/−Apoe−/− mice exhibited reduced atherosclerotic lesion size throughout the aorta, making HDAC9 a plausible target for pharmacologic prevention of atherosclerosis." (PMID 27796860, 2016). "Upregulation of HDAC9 expression was observed in human atherosclerotic plaques including in carotid, aortic, and femoral plaques, which appears to implicate the altered HDAC9 expression in promoting atherosclerosis." (PMID 27642596, 2016). "Taking all the evidence together, it is reasonable to hypothesize that SNP rs2107595 and HDAC9 expression may involve the progression of atherosclerosis, and thus exert stronger effects on unstable CAD than on SAP." (PMID 27494404, 2016). "Both in vivo and ex vivo knockout of Hdac9 could prevent EndMT through sustained endothelial protein expression and alleviate the increase in mesenchymal proteins, thus slowing the development of atherosclerosis." (PMID 35280995, 2022). "Subsequent functional annotation identified eight atherosclerosis-relevant candidate genes: transcription factors (KLF12, KLF6, KLF9, and MEF2C), epigenetic regulators (HDAC9), and signaling molecules (YAP1, SOCS6, and CDC25A)." (PMID 41373654, 2025). "Taken together, these results suggest that ICA can suppress lipid accumulation and mitigate inflammatory response in macrophages by activating the miR‐1271‐5p/HDAC9 signalling cascade, thereby providing new explanations for how ICA reduces atherosclerosis." (PMID 39698913, 2024). "Furthermore, both class IIa HDAC inhibition and genetic Hdac9 knockout reversed phenotypic endothelial cell changes that were induced by EndMT and led to favorable changes in atherosclerotic plaques, suggesting potential therapeutic benefit in the treatment of atherosclerosis." (PMID 34338228, 2021). "Here, we identified histone deacetylation, specifically that mediated by HDAC9 (a class IIa HDAC), as playing an important role in both EndMT and atherosclerosis." (PMID 34338228, 2021). "Moreover, in vitro histone deacetylase 9 (HDAC9) inhibition sustained EC marker expression and prevented mesenchymal transition, and HDAC9 KO in atherosclerosis-prone mice reduced plaque area, linking EndoMT to atherosclerosis progression." (PMID 40401523, 2025). "Histone deacetylase 9 (Hdac9), a member of the histone deacetylase II family, catalyzes the deacetylation of histone H3K16ac and other non-histone proteins, contributing to atherosclerosis and inflammation." (PMID 36823573, 2023). "These alternate studies do not dispel the notion that HDAC9 is important for atherosclerosis and CAD, but rather, they suggest that this locus causes CAD by governing Twist-related protein 1 (TWIST1), rather than HDAC9." (PMID 35714152, 2022). "Hdac9–/–Apoe–/– BMMs have reduced TNF‐α‐induced up‐regulation of pro‐inflammatory gene expression, and during the development of atherosclerosis, HDAC9 binds to, deacetylates and activates inhibitory kappa B kinase (IKK)‐α and β, driving inflammatory responses in macrophages and endothelial cells." (PMID 34145738, 2021). "Histone deacetylase 9 (HDAC9) plays an important role in transcriptional regulation, cell cycle progression and developmental events; moreover, it has been investigated as a candidate gene in a number of conditions, including the onset and progression of atherosclerosis." (PMID 32284067, 2020). "Conversely, the lack of histone deacetylase 9 (HDAC9) can mitigate endothelial–mesenchymal transition (EMT) that preserve plaques stability and decelerate the progression of atherosclerosis." (PMID 38405061, 2024).
non-small cell lung carcinoma (55 papers, 2012 to 2026). A group of at least three distinct histological types of lung cancer, including non-small cell squamous cell carcinoma, adenocarcinoma, and large cell carcinoma. "The overexpression of HDAC9 can enhance the tumorigenic potential of non-small cell lung cancer cells." (PMID 38920983, 2024). "Furthermore, inhibition of HDAC9 expression is a mechanism of melatonin to promote apoptosis in non-small cell lung cancer; the increased level of HDAC9 in patients with non-small cell lung cancer is correlated with worse overall survival and poor prognosis." (PMID 33789681, 2021). "Exogenous expression of HDAC9 reduced clonogenicity and proliferation in the immortalized airway epithelial NHBE-T and NSCLC (non-small cell lung cancer) cell lines A549 and H2087, respectively." (PMID 34318404, 2021).
gastric cancer (53 papers, 2008 to 2025). A primary or metastatic malignant neoplasm involving the stomach. "The TCGA database analysis showed that a high expression level of HDAC9 was positively associated with a poorly differentiated state of gastric cancer." (PMID 38920983, 2024). "A high level of HDAC9 was found to be positively associated with an advanced stage of gastric cancer." (PMID 38920983, 2024). "HDAC9 is reported to be regulated post-transcriptionally by several micro RNAs in retinal, oral, breast, and gastric cancer, and as being associated with poor prognosis." (PMID 32977608, 2020). "Bioinformatics analysis revealed that a high expression of HDAC9 was correlated with poor survival in patients with gastric cancers." (PMID 38920983, 2024). "It would be interesting to examine HDAC9 expression in the sera of gastric cancer patients in the future." (PMID 38920983, 2024). "Interfering with the production of HDAC9 protein improved the efficacy of the chemotherapeutic drug cisplatin in mice with stomach cancer." (PMID 31451695, 2019). "It would be also necessary to examine whether CAGEs and HDAC9 can promote anti-cancer drug resistance in other gastric cancer cell lines by establishing various anti-cancer drug-resistant cell lines." (PMID 38920983, 2024). "HDAC9 has been found to be upregulated in gastric cancer tissues and retinoblastoma tissues." (PMID 38920983, 2024). "HDAC9 expression has been reported to be upregulated in gastric cancer tissues." (PMID 38920983, 2024). "Similar results were reported in retinoblastoma and gastric cancer, however, the molecular pathway which links HDAC9 to the stemness property remains unknown." (PMID 32977608, 2020). "We examined whether soluble factors could regulate the expression of HDAC9 in gastric cancer cells." (PMID 38920983, 2024). "These seven proteins—(CRMP2, C-RAF, CYP17, c-KIT+ VEGFR, and HDAC9)were considered in this in silico study owing to their association with several cancers: breast cancer, liver cancer, prostate cancer, kidney cancer (for both C-KIT and VEGFR), and stomach cancer." (PMID 36354673, 2022). "Inhibiting histone deacetylase 9 (HDAC9), a protein that regulates gene expression, reduces stomach cancer cell growth." (PMID 31451695, 2019).
bladder cancer (49 papers, 2007 to 2026). "The mechanistic complexity of HDAC9-mediated deacetylation of bladder cancer cell substrates is further underlined by patterns of decreased HDAC9 expression being derived from publicly available microarray data." (PMID 30875794, 2019). "We constructed an immune signature for HDAC9, a vital epigenetic modification, to predict the survival status and treatment benefits in bladder cancer (BC)." (PMID 35239708, 2022). "Through regulating HDAC9, MiR-211 markedly suppresses bladder cancer cells migration and invasion." (PMID 35912006, 2022).
Obesity (49 papers, 2011 to 2026). Accumulation of substantial excess body fat. "To examine the potential association of HDAC9 with human obesity, we measured HDAC9 expression in human subcutaneous adipose tissue." (PMID 36078104, 2022). "More importantly, we reveal HDAC9 as a new target of butyrate in promoting the browning of white adipocytes, providing HDAC9 inhibition as a promising strategy to treat obesity and related complications." (PMID 40002674, 2025). "Although the overall statistical significance was modest, two loci—LYST (rs184772418) and HDAC9 (rs13247375)—demonstrated statistically significant interaction effects on HOMA-IR levels within obesity subgroups, based on an interaction p-value threshold <0.05." (PMID 40699860, 2025). "Multiple studies have concluded that HDAC9 contributes to a variety of chronic diseases, including cardiovascular diseases, cancer, and obesity." (PMID 38672510, 2024). "We previously reported that in obesity, HDAC9 expression is increased in the adipose tissues of humans and mice, in conjunction with impaired insulin sensitivity and glucose tolerance." (PMID 38672510, 2024). "Global genetic deletion of Hdac9 resulted in reduced weight gain, improved glucose tolerance and insulin sensitivity, and reduced ectopic lipid accumulation in high fat fed-mice, suggesting that HDAC9 plays a key role in obesity-related metabolic disease." (PMID 38672510, 2024). "Global deletion of Hdac9 protects against high-fat diet (HFD) induced obesity and metabolic disease in mice, and Immp2l is associated with food intake." (PMID 38483771, 2024). "Here, we investigated the impact of adipocyte-specific HDAC9 gene deletion on diet-induced obesity in male and female mice." (PMID 36078104, 2022). "One of the interesting aspects of this study is the differential role of adipose HDAC9 in obesity and metabolic disease in female versus male mice." (PMID 36078104, 2022). "In this study, we investigated the impact of adipocyte-specific HDAC9 gene deletion on metabolic function in HFD-induced obesity using both female and male mice." (PMID 36078104, 2022). "These contrasting results between male and female mice suggest a sex-dependent effect of adipocyte HDAC9 in obesity." (PMID 36078104, 2022). "We reported that, in obese male mice, histone deacetylase 9 (HDAC9) is upregulated in adipose tissues, and global deletion of HDAC9 protected against high fat diet (HFD)-induced obesity and metabolic disease." (PMID 36078104, 2022). "Our data indicate that female HFD-fed A-KO mice exhibit reduced obesity despite similar activity level and food consumption, akin to that reported in global HDAC9 KO mice, which was attributed to increased energy expenditure." (PMID 36078104, 2022). "Our findings provide evidence that adipocyte-expressed HDAC9 contributes to HFD-induced obesity only in female mice and suggest that cellular HDAC9 expression is regulated in a sex-dependent manner in adipose tissues." (PMID 36078104, 2022). "The results revealed that 18 of the DMR genes were associated with addiction and obesity (ADCY3; ADCY9; ATF4; CDK5R1; CHRNB2; GABRD; GABRG3; GNB1; GNB3; GRK5; HDAC4; HDAC9; MAP2K1; PDE11A; PDE2A; PDE3A; PPP1CA; SLC6A3)." (PMID 34389046, 2021). "In previous studies, HDAC9 was proposed as a potential therapeutic target for obesity, since lipid accumulation was prevented in HDAC9-knockdown mice fed chronic high-fat diets." (PMID 27247940, 2016). "Interestingly, Hdac9−/− mice were protected from diet-induced obesity and displayed improved insulin sensitivity and lower body weight." (PMID 40068774, 2025). "Moreover, we indicate that butyrate intervention prevented obesity accompanied by WAT browning, mechanistically associated with decreased HDAC9 in WAT." (PMID 40002674, 2025).
Obesity (continued). "Therefore, to examine the role of adipocyte-expressed HDAC9 in HFD-induced obesity and metabolic disease, HDAC9 floxed mice were bred with adiponectin-cre mice to generate adipocyte-specific HDAC9 knockout mice (A-KO) on a C57BL/6 background." (PMID 36078104, 2022). "Taken together, these data suggest that adipocyte-expressed HDAC9 is detrimental to adipocyte function in obese female mice and provide novel evidence of sex-related differences in HDAC9 cellular expression and contribution to obesity." (PMID 36078104, 2022). "Additionally, we only studied male mice; we recently reported sexual dimorphism with regard to the impact of adipocyte-specific Hdac9 gene deletion on high fat diet-induced obesity, wherein only the female adipose-specific Hdac9 knockout mice exhibited a strong phenotype." (PMID 38672510, 2024). "We reported that HDAC9 expression is upregulated in adipose tissues during obesity, in conjunction with impaired adipogenic differentiation, adipocyte hypertrophy, insulin resistance, and hepatic steatosis, all of which were alleviated by global genetic deletion of Hdac9." (PMID 38672510, 2024). "Moreover, HDAC9 has been shown to act as a negative regulator of adipogenesis, and genetic deletion of HDAC9 increases energy expenditure and adaptive thermogenesis, consequently protecting mice from high-fat diet-induced obesity, insulin resistance, and liver steatosis." (PMID 40002674, 2025). "Upregulated expression of Hdac9 has been reported to contribute to the pathogenesis of various chronic diseases, including cardiovascular diseases (CVD), cancer, liver disease, and obesity." (PMID 38672510, 2024). "We confirmed that HDAC9 is a transcriptional repressor of the cholesterol efflux ABCG1 gene expression, which is epigenetically modified in obesity and prediabetic states." (PMID 32410704, 2020). "Both HDAC9 and ABCG1 have been proposed as therapeutic targets for patients with obesity in separate previous studies; however, our data support a mechanistic pathway linking them to metabolic diseases." (PMID 32410704, 2020). "First, the specific role of HDAC9 in the anti-obesity effect of butyrate in vivo has not been shown." (PMID 40002674, 2025). "In conclusion, the experimental aging HDAC9 TG mice developed adipocyte hypertrophy, insulin resistance, and hepatic steatosis, independent of obesity." (PMID 38672510, 2024). "We identified an epigenetic link between adipogenesis and adipose tissue insulin resistance in the context of T2D risk associated with statin use, which has important implications as HDAC9 and ABCG1 are considered potential therapeutic targets for obesity and metabolic diseases." (PMID 32410704, 2020). "By adding 0.5% (w/w) HDAC8 and HDAC9 inhibitors to the culture medium, the GFP intensity in the transgenic bmm-expressing flies increased significantly compared with the control, indicating that obesity was suppressed." (PMID 27247940, 2016). "Here, we developed a novel transgenic (TG) mouse model to test whether overexpression of Hdac9 is sufficient to induce adipocyte hypertrophy, insulin resistance, and hepatic steatosis in the absence of obesity." (PMID 38672510, 2024). "Thus, the specific impact of aging (independent of obesity) on cellular distribution of HDAC9 expression in adipose tissues remain to be determined." (PMID 36078104, 2022). "Thus, deletion of HDAC9 in mature adipocytes is sufficient to protect female, but not male, mice against obesity-related metabolic disease." (PMID 36078104, 2022).
depression (46 papers, 2010 to 2025). "To clarify how ANXA2 alleviates depression-like behaviours caused by CRS or HDAC9 overexpression, we examined whether ANXA2 plays a role in dendritic spine development in the hippocampus." (PMID 37690046, 2023). "Herein, we found that HDAC9 was highly expressed in the hippocampus of chronic restraint stress (CRS) mouse model of depression." (PMID 37690046, 2023). "Upregulation of HDAC9 expression in hippocampal neurons of mice induced depression-like phenotypes, including anhedonia, helplessness, decreased dendritic spine density, and neuronal hypoexcitability." (PMID 37690046, 2023). "In previous SNP level analyses, ERG, NEBL, CADPS2, GABBR2, and HDAC9 genes have been reported to be related with neuropsychiatric diseases such as BD, depression disorder, and schizophrenia." (PMID 22901090, 2012). "Overall, we discovered a previously unrecognized role for HDAC9 in hippocampal neurons in the pathogenesis of depression, indicating that inhibition of HDAC9 might be a promising clinical strategy for the treatment of depressive disorders." (PMID 37690046, 2023). "In summary, our findings suggest that HDAC9 in hippocampal neurons may play a role in the pathophysiology of depression and that HDAC9 regulates the acetylation and ubiquitination of ANXA2." (PMID 37690046, 2023). "Our results provide the first evidence implicating HDAC9 in hippocampal neurons may play a role in pathophysiology of depression, implying its usefulness as a therapeutic target." (PMID 37690046, 2023). "In the present study, we monitored how HDAC9 overexpression or knockdown in hippocampal neurons affected depression-like behaviours in mice, finding evidence that HDAC9 upregulation may contribute to MDD." (PMID 37690046, 2023). "Together, these results suggest that the HDAC9 level in the hippocampus is elevated in mice with depressive-like behavior and that this increase in HDAC9 expression is sufficient to induce depressive behaviors, indicating that HDAC9 can contribute to depressive disorders." (PMID 37690046, 2023). "HDAC9 upregulation may protect ANXA2 from ubiquitin-dependent degradation, thereby contributing to depression-like symptoms." (PMID 37690046, 2023). "Moreover, we found that after experiencing CRS, there was no significant change in the distribution of HDAC9 in neurons of other depression related brain regions such as Lateral hypothalamus (LH), Lateral habenula (LHB) and Prelimbic cortex (PrL)." (PMID 37690046, 2023). "This may explain why we believe that hippocampal neuron HDAC9 plays a key role in CRS induced depression rather than other HDACs." (PMID 37690046, 2023).
cervical carcinoma (42 papers, 2005 to 2025). A carcinoma arising from either the exocervical squamous epithelium or the endocervical glandular epithelium. "Recent studies have observed that HDAC9 plays an important role in tumorigenesis and exerts a dual role in different cancers, including cervical cancer, medulloblastoma and acute lymphoblastic leukemia." (PMID 25760078, 2015). "High expression of HDAC9 has been reported in cervical cancer." (PMID 25760078, 2015). "Similarly, in cervical carcinoma, the HDAC9 gene was identified by CGH array in a region of high copy number gain thus suggesting that an increase in gene copy number could also be involved in HDAC9 gene overexpression." (PMID 31099456, 2019). "As per our earlier discussion, the role of PTPN14, CDK2 and HDAC9 in tumor suppression and the interaction with HPV E7 oncoprotein is observed stating that these targets can be potential druggable targets for cervical cancer." (PMID 35989375, 2022).
asthma (41 papers, 2006 to 2025). "While DPP10 and HDAC9 were implicated as risk loci for asthma susceptibility and/or severity and related phenotypes, this study is the first to indicate an association of these genes with ICS response." (PMID 32119686, 2020). "We report that THSD4, HIVEP2, DPP10, HDAC9 and other genes within inflammatory response pathways and with definitive roles in asthma susceptibility, severity, and exacerbations, are also asthma pharmacogenes." (PMID 32119686, 2020). "A fiber-rich diet during pregnancy protected the offspring against the onset of asthma, probably via inhibition of histone deacetylase 9 (HDAC9) mediated by acetate resulting in higher gene transcription of Foxp3 in Tregs." (PMID 34054875, 2021). "Furthermore, an increased activity of ILC2s plays a key part in asthma development, and inulin intervention has been reported to reduce the number of airway eosinophils and improve asthma by suppressing HDAC9 expression in people suffering from asthma." (PMID 37638034, 2023). "Indeed, roles for other epigenetic effectors, including histone methylation and acetylation marks, have been implicated in the severity of asthma, and a genome-wide association study identified significant histone modifying enzyme (KDM2A, KDM4C, HDAC4, HDAC7 and HDAC9) polymorphisms in asthma." (PMID 40057553, 2025). "In addition to THSD4 and HIVEP2, age-by-genotype interactions also prioritized genes previously identified as asthma candidate genes, including DPP10, HDAC9, TBXAS1, FBXL7, and GSDMB/ORMDL3, as pharmacogenomic loci as well." (PMID 32119686, 2020).